UBE2D3 (ubiquitin conjugating enzyme E2 D3)
Description:
Accepts ubiquitin from the E1 complex and catalyzes its covalent attachment to other proteins. In vitro catalyzes 'Lys-11'-, as well as 'Lys-48'-linked polyubiquitination. Cooperates with the E2 CDC34 and the SCF(FBXW11) E3 ligase complex for the polyubiquitination of NFKBIA leading to its subsequent proteasomal degradation. Acts as an initiator E2, priming the phosphorylated NFKBIA target at positions 'Lys-21' and/or 'Lys-22' with a monoubiquitin. Ubiquitin chain elongation is then performed by CDC34, building ubiquitin chains from the UBE2D3-primed NFKBIA-linked ubiquitin. Also acts as an initiator E2, in conjunction with RNF8, for the priming of PCNA. Monoubiquitination of PCNA, and its subsequent polyubiquitination, are essential events in the operation of the DNA damage tolerance (DDT) pathway that is activated after DNA damage caused by UV or chemical agents during S-phase. Associates with the BRCA1/BARD1 E3 ligase complex to perform ubiquitination at DNA damage sites following ionizing radiation leading to DNA repair. Targets DAPK3 for ubiquitination which influences promyelocytic leukemia protein nuclear body (PML-NB) formation in the nucleus. In conjunction with the CBL E3 ligase, targets EGFR for polyubiquitination at the plasma membrane as well as during its internalization and transport on endosomes. In conjunction with the STUB1 E3 quality control E3 ligase, ubiquitinates unfolded proteins to catalyze their immediate destruction. Together with RNF135, catalyzes the viral RNA-dependent 'Lys-63'-linked polyubiquitination of RIGI to activate the downstream signaling pathway that leads to interferon beta production. Together with ZNF598, catalyzes ubiquitination of 40S ribosomal proteins in response to ribosome collisions. In cooperation with the GATOR2 complex, catalyzes 'Lys-6'-linked ubiquitination of NPRL2.
Synonyms: UBCH5C; E2(17)KB3; UBC4/5
Tractability: Small molecule: a structure with a bound ligand is known; a high-quality ligand is known. Antibody: UniProt places it where antibodies can reach, with high confidence; its Gene Ontology location is reachable by antibodies, with medium confidence. PROTAC: ubiquitination databases record sites on it; its protein half-life has been measured; a small molecule that binds it is known.
Target class: Enzyme; Transferase
Gene: Protein-coding gene on chromosome 4 (102,793,516 to 102,869,287, reverse strand). Ensembl gene ENSG00000109332.
Subcellular location: Cell membrane; Endosome membrane
Subcellular location (Human Protein Atlas): Cytosol; Plasma membrane
Pathways (Reactome):
Immune System: Antigen processing: Ubiquitination & Proteasome degradation; IKK complex recruitment mediated by RIP1; Inactivation of CSF3 (G-CSF) signaling; Negative regulators of DDX58/IFIH1 signaling; TICAM1, RIP1-mediated IKK complex recruitment
Metabolism of proteins: E3 ubiquitin ligases ubiquitinate target proteins; Neddylation; ZNF598 and the Ribosome-associated Quality Trigger (RQT) complex dissociate a ribosome stalled on a no-go mRNA
Signal Transduction: Downregulation of SMAD2/3:SMAD4 transcriptional activity; Regulation of TNFR1 signaling; Signaling by BMP
Autophagy: PINK1-PRKN Mediated Mitophagy
Cellular responses to stimuli: Oxygen-dependent proline hydroxylation of Hypoxia-inducible Factor Alpha
Protein localization: Peroxisomal protein import
Gene Ontology:
Molecular function: protein binding; ubiquitin conjugating enzyme activity; ubiquitin protein ligase activity; ubiquitin-protein transferase activity
Biological process: positive regulation of establishment of protein localization to mitochondrion; proteasome-mediated ubiquitin-dependent protein catabolic process; protein autoubiquitination; protein K11-linked ubiquitination; protein K48-linked ubiquitination; protein K6-linked ubiquitination; protein monoubiquitination; protein polyubiquitination; protein ubiquitination; negative regulation of BMP signaling pathway; negative regulation of transcription by RNA polymerase II; protein modification process; ubiquitin-dependent protein catabolic process
Cellular component: endosome membrane; extracellular exosome; plasma membrane; cytosol; nucleoplasm
Genetic constraint (gnomAD): Loss-of-function variants: 0 observed, 13.56 expected, observed/expected ratio (o/e) 0, 90% interval 0 to 0.22. The upper end of that interval is the gene's LOEUF score, 0.22, which puts it in group 1 of 6, group 1 being the genes least tolerant of losing a copy. Missense variants: 21 observed, 141.39 expected, observed/expected ratio (o/e) 0.15, 90% interval 0.1 to 0.21. Synonymous variants: 41 observed, 46.46 expected, observed/expected ratio (o/e) 0.88, 90% interval 0.69 to 1.14.
Homologues: Orthologues: mouse Ube2d3 (98% identical), pig UBE2D3 (98% identical), macaque UBE2D3 (96% identical), rabbit UBE2D3 (95% identical), rat Ube2d2 (95% identical), zebrafish ube2d2l (95% identical), tropical clawed frog ube2d3 (93% identical), zebrafish ube2d3 (93% identical), guinea pig UBE2D3 (93% identical). Paralogues in human: UBE2D2 (97% identical), UBE2D4 (91% identical), UBE2D1 (86% identical), UBE2E3 (64% identical), UBE2E1 (63% identical), UBE2E2 (63% identical), UBE2L5 (39% identical), UBE2L3 (37% identical), UBE2L6 (37% identical), UBE2Q2 (32% identical), UBE2Q1 (31% identical), UBE2QL1 (25% identical).
Diseases named in the same sentence as UBE2D3 in open-access papers:
UBE2D3 is named in the same sentence as 34 diseases in open-access papers, as found by Europe PMC text mining. Sharing a sentence is not in itself a finding about the gene and the disease. The quoted sentences say what the papers report.
breast carcinoma (10 papers, 2012 to 2024). "UBE2D3 has been implicated to be involved in the development and progression of various types of cancer including esophageal cancer, breast cancer and acute promyelocytic leukemia." (PMID 34195079, 2021). "Collectively these findings suggest that UBE2D3 participates in the process of hTERT-mediated radiosensitivity in human breast cancer MCF-7 cells by regulating hTERT and cyclin D1." (PMID 23741361, 2013). "We previously found that it is bound to hTERT, and UBE2D3 could attenuate radiosensitivity of human breast cancer cells." (PMID 27105523, 2016). "Moreover, UBE2D3 could modulate the radiosensitivity of breast cancer through regulating the activity of human telomerase reverse transcriptase." (PMID 34195079, 2021).
esophageal cancer (5 papers, 2015 to 2023). A primary or metastatic malignant neoplasm involving the esophagus. "For instance, the ubiquitin-conjugating E2 enzyme variant UBE2D3 has been identified as a regulator of esophageal cancer radiosensitivity, influencing it through various mechanisms." (PMID 38137461, 2023). "In conclusion, the present study demonstrated that hTERT and UBE2D3 expression are negatively correlated, and that the two proteins demonstrate a strong association with the prognosis in esophageal cancer." (PMID 25789002, 2015). "The E2 family member UBE2D3 not only impacts radiosensitivity in esophageal cancer but also in breast cancer." (PMID 38137461, 2023). "A previous study demonstrated that UBE2D3 plays a significant role in the development of esophageal cancer." (PMID 31844595, 2019). "It was subsequently identified that tumor location, lymph node status and UBE2D3 expression level were independent prognostic factors in esophageal cancer." (PMID 25789002, 2015). "A previous study indicated that UBE2D3 was a protective factor for esophageal cancer patients and its knockdown could significantly increase radioresistance and maintain telomerase activity." (PMID 34195079, 2021). "Thus, the aim of the present study was to elucidate the clinical significance of hTERT and UBE2D3 expression in esophageal cancer." (PMID 25789002, 2015). "Univariate analysis indicated that tumor location, T, N and TNM stage, and hTERT and UBE2D3 expression may predict esophageal cancer prognosis, therefore, these factors were integrated into multivariate analysis using Cox proportional hazards analysis." (PMID 25789002, 2015). "Therefore, the protein expression levels of hTERT and UBE2D3 were evaluated in 150 esophageal cancer and 30 adjacent healthy tissue samples by performing immunohistochemical analysis." (PMID 25789002, 2015). "Furthermore, UBE2D3 expression levels were significantly lower in poorly-differentiated, advanced N stage and recurrent cases of esophageal cancer (P=0.007, P=0.016 and P=0.008, respectively)." (PMID 25789002, 2015). "Furthermore, UBE2D3, lymph node status and tumor location were independent prognostic factors for esophageal cancer in multivariate analysis." (PMID 25789002, 2015). "It was identified that the expression of hTERT in the esophageal cancer tissues was significantly higher compared with that of the adjacent tissues (P=0.015), however, the expression of UBE2D3 was significantly lower in esophageal cancer tissues than the adjacent tissues (P=0.001)." (PMID 25789002, 2015). "Thus, it is proposed that UBE2D3 expression may be involved in the progression of esophageal cancer." (PMID 25789002, 2015). "In addition, UBE2D3 appeared to be an independent prognostic factor for esophageal cancer." (PMID 25789002, 2015). "In conclusion, the findings of the present study indicated that hTERT and UBE2D3 proteins appear to be involved in the development of esophageal cancer, that UBE2D3 may a positive prognostic factor for esophageal cancer, and that UBE2D3 and hTERT expression levels are inversely correlated." (PMID 25789002, 2015). "Furthermore, the current study identified that the expression of UBE2D3 was significantly lower in the esophageal cancer tissues compared with the adjacent healthy tissues, as well as significantly lower in the cancer tissues with lymph node involvement and poor differentiation." (PMID 25789002, 2015). "Furthermore, the expression of UBE2D3, lymph node involvement and tumor location were independent predictive prognostic factors; thus, UBE2D3 expression may be a promising prognostic biomarker in esophageal cancer." (PMID 25789002, 2015). "It has been shown that the expression of UBE2D3 was extremely low in all of the cancerous cell lines including esophageal cancer cell line but not in normal tissues." (PMID 27105523, 2016).
glioma (3 papers, 2021 to 2024). A benign or malignant brain and spinal cord tumor that arises from glial cells (astrocytes, oligodendrocytes, ependymal cells). "Our study aims to explore the function and underlying mechanism of UBE2D3 in the development of glioma." (PMID 34195079, 2021). "The expression of UBE2D3 was higher in glioma cell lines especially in T98G and U87 compared with normal brain tissues." (PMID 34195079, 2021). "In 86 glioma specimens, the expression of UBE2D3 and SHP-2 exhibited reversed expression pattern (p < 0.05)." (PMID 34195079, 2021). "By analysis with The Cancer Genome Atlas-Glioblastoma multiforme (TCGA-GBM) dataset, we found that UBE2D3 was highly expressed in glioma and it is positive correlation with glycolysis, apoptosis, and STAT3 pathway." (PMID 34195079, 2021). "In contrast, UBE2D3 seemed to play an oncogenic role in glioma since our study revealed that UBE2D3 was highly expressed in GBM compared to normal brain tissues." (PMID 34195079, 2021). "Our study was conducted to explore the role of UBE2D3 and its molecular mechanism in the pathogenesis of glioma, aiming to provide a novel target for glioma treatment." (PMID 34195079, 2021). "Our data firstly showed that the glycolysis process and the expression of glycolytic enzymes, HK-2 and PFKL) in glioma cells were suppressed upon the knockdown of UBE2D3." (PMID 34195079, 2021). "Then, we explore the effects of UBE2D3 knockdown in the biological functions of glioma cell lines." (PMID 34195079, 2021). "The inhibition of UBE2D3 significantly reduced the tumor growth in mice xenograft models, indicating that UBE2D3 could be a potential target for glioma treatment." (PMID 34195079, 2021). "Overexpressed SHP-2 could reverse the effect of UBE2D3 and they shared contrary expression patterns in glioma and normal brain tissues." (PMID 34195079, 2021). "Besides, SHP-2 exhibited reversed expression pattern compared with UBE2D3 in glioma tissues." (PMID 34195079, 2021). "Further, we detected the expression pattern of UBE2D3 and SHP-2 in glioma specimens to validate their interactions." (PMID 34195079, 2021). "In summary, our study revealed that UBE2D3 could promote the ubiquitination of SHP-2, which activated STAT3 pathway and promoted glioma proliferation as well as glycolysis." (PMID 34195079, 2021). "Our preliminary data showed that a STAT3 inhibitor could inhibited UBE2D3 overexpression-induced STAT3 phosphorylation in glioma cells (data not shown)." (PMID 34195079, 2021). "However, we did not reveal the underlying mechanism of UBE2D3 and SHP-2 in regulating the glycolysis of glioma cells." (PMID 34195079, 2021).
acute promyelocytic leukemia (2 papers, 2015 to 2023). An aggressive form of acute myeloid leukemia (AML), characterized by arrest of leukocyte differentiation at the promyelocyte stage, due to a specific chromosomal translocation t(15;17) in myeloid cells. "Upregulation of UBE2D3 in acute promyelocytic leukemia cells leads to the ubiquitination of cyclin D1 and its degradation in the proteasome." (PMID 25789002, 2015). "Interestingly, UBE2D3 was found upregulated in ATRA-treated NB4 acute promyelocytic leukemia cells, leading to UBE2D3-mediated degradation of cyclin D1 and cell cycle arrest." (PMID 37059365, 2023).
autism (2 papers, 2016 to 2025). Persistent deficits in social interaction and communication and interaction as well as a markedly restricted repertoire of activity and interest as well as repetitive patterns of behavior. "Conversely, upregulation of the UBE2D3 module indicated activation of endoplasmic reticulum stress responses, a contributor to autism." (PMID 41367385, 2025).
myocardial infarction (2 papers, 2024 to 2025). Gross necrosis of the myocardium, as a result of interruption of the blood supply to the area, as in coronary thrombosis. "In myocardial infarction, four cuproptosis-related genes—Dbt, Dlat, Ube2d1, and Ube2d3—were identified as potential diagnostic markers through random forest and the least absolute shrinkage and selection operator (LASSO) analysis." (PMID 40124544, 2025). "The cuproptosis-related gene Ube2d3 emerged as a central biomarker in myocardial infarction, with findings showing that Ube2d3 promotes hypoxia-induced damage in AC16 cells by inducing cuproptosis." (PMID 40124544, 2025).
schizophrenia (2 papers, 2016 to 2021). A major psychotic disorder characterized by abnormalities in the perception or expression of reality. "Among the FG loci with sex-homogeneous effects, variants at the MANBA/UBE2D3, NFATC3, and IGF1R provided insights into pathways involved in glucose homeostasis and relationships with other complex phenotypes, including neurodegeneration, schizophrenia, and cancer." (PMID 33402679, 2021).
Alzheimer disease (1 paper, 2021). A progressive, neurodegenerative disease characterized by loss of function and death of nerve cells in several areas of the brain leading to loss of cognitive function such as memory and language. "Interestingly, this inflammatory pathway is often noted for its association to AD, while UBE2D3 has been proposed as a potential biomarker for Alzheimer’s disease." (PMID 33964127, 2021).
autoimmune disease (1 paper, 2021). A disorder resulting from loss of function or tissue destruction of an organ or multiple organs, arising from humoral or cellular immune responses of the individual to their own tissue constituents. "Interestingly, the lead SNP at the MANBA/UBE2D3 locus, rs223486, is an intergenic variant located in a region (±500 kb) that harbors several other genes (CISD2, NFKB1, SLC9B1/2, BDH2 and CENPE) with reported inflammatory and autoimmune disease associations." (PMID 33402679, 2021).
bladder cancer (1 paper, 2025). "Further multivariate Cox regression confirmed that HIF3A, DDB1, COPS2, and UBE2D3 may independently indicate bladder cancer prognosis." (PMID 40524221, 2025). "The analysis revealed that UBE2D3 and COPS2 are highly expressed in seven different bladder cancer cell types, whereas HIF3A and CUL1 are expressed at low levels in the same cell clusters." (PMID 40524221, 2025).
choroideremia (1 paper, 2019). Choroideremia (CHM) is an X-linked chorioretinal dystrophy characterized by progressive degeneration of the choroid, retinal pigment epithelium (RPE) and retina. "Because the proteomics represents pooled samples with one pooled sample per group, we selected two proteins for validation, ubiquitin-conjugating enzyme E2D 3 (Ube2d3) and choroideremia-rab escort protein 1 (Chm) in individual replicate samples." (PMID 30629705, 2019).
colon cancer (1 paper, 2023). "As such, these findings strongly supported a role for the UBE2D3/IκBa/NF-κB signaling axis as a mediator of the ability of P14AS to promote colon cancer progression." (PMID 38041015, 2023). "Moreover, the beneficial impact of P14AS on colon cancer cell growth was eliminated when cells were treated with miR-23a-5p inhibitors or UBE2D3 was silenced." (PMID 38041015, 2023).
gestational diabetes mellitus (1 paper, 2025). "A transcriptomic profiling analysis of trophoblast isolated from gestational diabetes mellitus (GDM) defined 8 ubiquitin-conjugating enzymes (UBE) splice variants (UBE2D3 variants 1, 3, 4, 5, 6, 7, 9 and UBE2V1 variant 4) are associated with increased maternal fasting plasma glucose." (PMID 40410732, 2025).
leukemia (1 paper, 2026). A malignant (clonal) hematologic disorder, involving hematopoietic stem cells and characterized by the presence of primitive or atypical myeloid or lymphoid cells in the bone marrow and the blood. "Functionally, UBE2D3 acts as a critical downstream effector that sustains leukemia cell proliferation and survival through MYC-dependent signaling." (PMID 41926643, 2026).
multiple sclerosis (1 paper, 2025). A progressive autoimmune disorder affecting the central nervous system resulting in demyelination. "GPX1, RCN1, and UBE2D3 exhibited AUC values above 0.7 in both datasets, indicating their potential as biomarkers for multiple sclerosis." (PMID 40650067, 2025).
oesophageal cancer (1 paper, 2025). "In other studies The increased expression of UBE2D3 and PUM2 is associated with a better prognosis in patients with oesophageal cancer." (PMID 40524221, 2025).
osteoporosis (1 paper, 2025). A condition of reduced bone mass, with decreased cortical thickness and a decrease in the number and size of the trabeculae of cancellous bone (but normal chemical composition), resulting in increased fracture incidence. "It showed that in osteoporosis patients, CP (P < 0.01), LIPT1 (P < 0.05), SLC25A3 (P < 0.001), and UBE2D3 (P < 0.01) were upregulated, while the expression levels of CDKN2A (P < 0.05), DBH (P < 0.01), DLST (P < 0.05), LOXL2 (P < 0.05), SLC31A1 (P < 0.05), and UBE2D1 (P < 0.01) were downregulated." (PMID 40980812, 2025).
Parkinson disease (1 paper, 2023). A progressive degenerative disorder of the central nervous system characterized by loss of dopamine producing neurons in the substantia nigra and the presence of Lewy bodies in the substantia nigra and locus coeruleus. "Interesting to note, as it supports a potential role for UBE2D3 in pathology related to its functions in RQC and (autophagic) PQC, the expression of UBE2D3 was found decreased at early stages of Parkinson’s disease in mouse brains." (PMID 37059365, 2023).